RNU6-155P (RNA, U6 small nuclear 155, pseudogene)
Gene: Small nuclear RNA gene on chromosome 6 (75,768,059 to 75,768,158, reverse strand). Ensembl gene ENSG00000252156.
Homologues: Orthologues: dog U6 (75% identical), pig U6 (75% identical), pig U6 (74% identical), guinea pig U6 (64% identical), mouse Gm25335 (60% identical). Paralogues in human: RNU6-820P (82% identical), RNU6-35P (81% identical), RNU6-378P (81% identical), RNU6-1152P (80% identical), RNU6-144P (80% identical), RNU6-25P (80% identical), RNU6-31P (80% identical), RNU6-1 (79% identical), RNU6-1060P (79% identical), RNU6-12P (79% identical), RNU6-13P (79% identical), RNU6-140P (79% identical), and 1286 more.